CDK4 (cyclin dependent kinase 4)
Diseases named in the same sentence as CDK4 in open-access papers (continued):
Sharing a sentence is not in itself a finding about the gene and the disease.
cancer (continued). "However, resistance to CDK4/6 inhibitors is prevalent in other cancer cell types including HCC, thus limiting the utility of these drugs in clinics." (PMID 37744274, 2023). "Cdk6−/− MCA205 cells proliferated at a slower rate and formed fewer colonies than WT and Cdk4−/− MCA205 cells, indicating Cdk6-deficiency could directly affect cancer cell proliferation in vitro." (PMID 37833461, 2023). "A PDX cancer mouse model study showed that resistance to CDK4/6 inhibitors could be alleviated by adding PI3K inhibitors, regardless of PIK3CA mutation." (PMID 36978140, 2023). "Studies have demonstrated that amplification of the cyclin D1 gene could make some cancers more dependent on the CDK4/6 pathway and more vulnerable to CDK4/6 inhibition." (PMID 36765923, 2023). "Both in vitro and in vivo studies have consistently confirmed the anti-cancer potential of fucoidan via the inhibition of angiogenesis, induction of cell cycle arrest and apoptosis and down regulation of CDK4, cyclin D1 and cyclin D2 in cancer cells [reviewed in more details in and]." (PMID 36874031, 2023). "Retinoblastoma-binding protein 7 (RBBP7), an important component of chromatin metabolism-regulating complex, is overexpressed in various cancer types, enhancing cancer cell proliferation, invasion and stemness, increasing cyclin-dependent kinase 4 (CDK4) expression." (PMID 38067326, 2023). "Downstream events of this altered cytokine regulation could hinder cancer immunoediting and interfere with the immunologic effects of both CDK4/6 inhibitors and HER2-targeted therapies." (PMID 38023235, 2023). "The efficacy of CDK4/6 inhibitors is now being explored in other diseases, as it has been discovered that CDK4/6 may play a role in pathological conditions beyond cancer." (PMID 37686364, 2023). "Due to its deregulation, many cancer cells are addicted to CDK4/6 activity." (PMID 37964967, 2023). "As CDK4/6 inhibitors arrest cells in the G1 phase, they were initially considered to be incompatible in combination with DNA-damaging and antimitotic therapeutics, which are often used as a standard of care for most cancer types." (PMID 36765923, 2023). "CDK4/6 play important role in the proliferation of cancer cells." (PMID 37415164, 2023). "Therefore, CDK4/6 as an important antitumor target, was developed as a chemotherapeutic drug for cancer therapy." (PMID 37771436, 2023). "Additionally, the Western blot analysis revealed that the knockdown of SNHG3 significantly reduced the protein levels of proteins involved in the cell cycle (CDK6, CDK4, and Cyclin D1) as well as cancer metastasis (N-Cadherin, Vimentin, and MMP9)." (PMID 37348024, 2023). "The literature describes multiple mechanisms through which TGF-β may promote resistance to BRAFi/MEKi, EGFRi, HER2i, and CDK4/6i by activating alternative signaling routes, including proliferative and anti-apoptotic pathways across different cancer types." (PMID 38203214, 2023). "Even in RB negative cancers, CDK4/6 inhibitors work by inhibiting cell division or causing apoptosis without involving RB." (PMID 36768557, 2023). "Furthermore, these results, pointing out the cancer-promoting role of CDK4 and EXT2 specifically in GBM, allowed the contemplation of a similar function also in the PBZ." (PMID 36769158, 2023). "However, CDK4/6 inhibitors have yet to result in major clinical efficacy in other cancers and targeting other CDKs have yet to result in clinical applications." (PMID 37111276, 2023). "Data from the The Cancer Genome Atlas (TCGA) and Genotype Tissue Expression (GTEx) database, consulted by OncoDB, showed that CDK4 and EXT2 mRNA expression increased with malignancy augmentation, rising from normal brain tissue, passing through LGG, ending in GBM." (PMID 36769158, 2023). "Unexpectedly, we also found that P-Tex cells expressed CDK4 genes as high as cancer cells, which could be simultaneously inhibited by the CDK4 inhibitors." (PMID 36811599, 2023).
cancer (continued). "Ramifications of these results for cancer progression, anti-CDK4/6- and IC-therapies are discussed." (PMID 37230983, 2023). "Overexpression of survivin in the nuclei of cancer cells promotes the G1–S cell cycle transition by releasing p21 (known as a cyclin-dependent kinase [Cdk] inhibitor 1) from Cdk4 to activate the cyclin D1/Cdk4 complex, leading to the phosphorylation of the protein retinoblastoma." (PMID 37915752, 2023). "Notably, CDK4, which was highly expressed in cancer cells, was also found to be highly expressed in the P-Tex cells." (PMID 36811599, 2023). "Moreover, approximately 30% of those in second-line therapy progressed within 6 months despite the outstanding efficacy of CDK4/6is, indicating that these patients had cancers resistant to CDK4/6is, resulting in poor prognoses." (PMID 37486454, 2023). "The founding discoveries in the early 1990s provided proof of principle that Cdk4 inhibition might retard cancer cell development." (PMID 37373242, 2023). "In this review, we highlight the significant functions of CDK4/6 in the control of cell cycle progression in normal cells and describe the several methods by which deregulation of the CDK4/6 pathway leads to unchecked cancer cell proliferation." (PMID 36768557, 2023). "Because multiple cancer treatments may reduce CDK4 expression, this protein has been regarded as a critical target protein in a variety of malignancies." (PMID 37894904, 2023). "Also, at the cellular level, CDK4/6 inhibitor treatment stimulates anti‐cancer immune responses, including reduced Treg and elevated levels of immunostimulatory molecules." (PMID 36457244, 2023). "Given that Cdk4 activation regulates cancer stemness and the expression of stem markers, we can speculate that Cdk4 could control the acquisition of hybrid phenotypes, gradually more and more aggressive, characterized by an intermediate molecular state." (PMID 37373242, 2023). "CKMT1 might also alter cancer metabolism and energy generation through phosphorylating and interacting with CDK4 in the developing process of lung carcinogenesis." (PMID 37061730, 2023). "Notably, CDK4 was highly expressed in P-Tex2 cells, cancer epithelial cells, and fibroblasts, while MKI67 was highly expressed in P-Tex1 clusters." (PMID 36811599, 2023). "Overall, these novel findings may have implications for the design of treatment modalities combining CDK4/6 inhibition and T cell-based cancer immunotherapeutic strategies." (PMID 36817127, 2023). "During the G1-S checkpoint, CDK4/6 activation by the AR axis contributes to cancer cell proliferation; among the mechanisms of resistance to NHA, the upregulation of cyclin D1 (whose association with CDK4/6 is crucial for the transition from G1 to S phase) was described." (PMID 37894312, 2023). "Thus, CDK4/6 inhibition can result in G1 arrest of the cell cycle, making it a potent and successful approach for cancer therapy." (PMID 36768557, 2023). "These pathways and mechanisms are complex and interconnected, and their involvement in mediating resistance to CDK4/6i may vary depending on the specific cancer type and individual patient characteristics." (PMID 37475713, 2023). "Recently, therapeutic synergy for combination of CDK4/6i and PARPi has been demonstrated in various solid tumors, including those of the breast, ovarian, and pancreas, which provides a promising approach for treatment of these cancers regardless HR status." (PMID 35270034, 2022). "If, in addition to Rb, Cdk4/6 also directly control RNAPII activity during cell cycle entry via CTD phosphorylation, then the molecular mechanism by which Cdk4/6 inhibitors exert their effect in the treatment of cancer may need to be revisited." (PMID 35163213, 2022). "However, only a CDK4/6 inhibitor is used in the clinical treatment of malignant tumors, and the exact efficacy and safety of other CDK inhibitors are still uncertain." (PMID 36078096, 2022).
cancer (continued). "However, cIAP-based degraders induced a combined degradation of CDK4/6 and IAPs resulted in synergistic effects on cancer cell growth." (PMID 35680848, 2022). "This implies that CDK4/6 inhibition may impair the ability of cancer cells to repair the induced DNA damage via NHEJ—as well as HR-mediated DNA repair." (PMID 35717443, 2022). "Therefore, although CDK4/6 inhibitors are promising agents for the future senescence‐based cancer therapy, further investigation is warranted to establish their effective usage." (PMID 35674109, 2022). "For example, CDK4/6 is hyperactivated in many human cancers as a result of overexpression of positive regulators such as CYCLIN D, inactivation of INK4 and CIP/KIP inhibitors, or deletion and/or epigenetic alterations of substrates such as RB [reviewed in 1, 118, 119]." (PMID 36051751, 2022). "While Cdk4 null-mutant mice underscore a role for the gene in normal cell development, this animal model has also shed light on the role that this kinase plays in the genesis and progression of cancer, particularly that of the mammary gland." (PMID 36051751, 2022). "Altogether, we believe F9 could be considered as a potential biomarker to predict CDK4/6 inhibitor response when used as first-line treatment in cancer." (PMID 35184131, 2022). "To evaluate whether such detrimental effect is also exerted by CDK4/6i‐induced senescent cells, we compared the physical activity of cancer‐free mice exposed to abemaciclib or doxorubicin." (PMID 34985783, 2022). "CDK4/6 is a key regulator of the transition from G1 to S phase and the inhibition of CDK4/6 blocks progression of the cell cycle from the G1 to S phase in cancer cells." (PMID 35350768, 2022). "However, intrinsic or acquired resistance to CDK4/6 inhibitors has limited their application in cancer therapy." (PMID 36432068, 2022). "CDK4/6 inhibitors represent a potential breakthrough in cancer treatment." (PMID 36003796, 2022). "In addition, the LAR subgroup of TNBC showed a high sensitivity to CDK4/6 inhibitors (CDK4/6i) in vitro and in vivo, and CDK4/6i sensitize PIK3CA mutant cancers to PI3Ki." (PMID 36579519, 2022). "In addition, numerous clinical trials are performed with this combinatorial treatment in various cancer types by using ribociclib, palbociclib, abemaciclib or dalpiciclib as CDK4/6 inhibitors and different MAPK inhibitors." (PMID 35938171, 2022). "It is therefore critical to determine how and why G1‐arrested cells eventually become senescent because this may help to inform ongoing clinical trials assessing CDK4/6 inhibition alongside immunotherapy (currently 14 trials in eight different cancer types)." (PMID 35037284, 2022). "However, cancer cells resistant to these CDK4 inhibitors still rely on CCND1 for proliferation, suggesting that new strategies to suppress CCND1-CDK4 are urgently needed." (PMID 35233069, 2022). "Given that the CDK4/6 ‐ retinoblastoma protein (Rb) axis is essential for the transition from G1 to S phase in the cell cycle, it is a popular drug target in several types of cancer." (PMID 35711853, 2022). "An initial treatment of cancer cells with CDK4/6 inhibitors may prevent mitosis-targeting mechanism of paclitaxel cytotoxicity." (PMID 36185294, 2022). "RB binds to the NFκB protein: in PC cell lines, CDK4/6-phosphorylated RB may promote cancer immunity through inhibition of NF-kB transcriptional activity and of PD-L1 expression." (PMID 35203446, 2022). "With the clinical success of CDK4/6 inhibitors, it is becoming increasingly clear that targeting individual cell cycle components may be an effective anti-cancer strategy." (PMID 35765111, 2022). "Because the pharmacologic inhibition of CDK4/6 has been established as tolerable in cancer treatment, it could also be beneficial in patients with RA due to its chondroprotective and anti-inflammatory effects." (PMID 34849618, 2022). "Besides quiescence and senescence, CDK4/6 inhibitors can also induce apoptosis in certain cancer cells." (PMID 35327487, 2022).
cancer (continued). "Induction of autophagy by CDK4/6 inhibitors is a common resistance mechanism in cancer treatment." (PMID 35938171, 2022). "Interestingly, cyclin-dependent kinase 4, with high importance in cancer immunity, was the highest abundant interaction among the novel, gained interactions of the mutant KLF2." (PMID 36466816, 2022). "Our results suggested that the combination of CDK4/6 inhibitor with CCL5 inhibitor or senotherapy could be considered to improve the curative effect and reduce the side effect of CDK4/6 inhibitors in the treatment of cancer." (PMID 37181790, 2022). "This may also open potential treatment perspectives for cancer lines that have elevated CDK4 activities and show high proliferation rates." (PMID 35054996, 2022). "Although Cdk4/6 inhibitors have a multitude of effects on cancer cells, one important effect is believed to be the breaking of this feedback loop by preventing phosphorylation of Rb and its dissociation from E2F, such that E2F cannot activate transcription and the cells arrest at the G1/S boundary." (PMID 35163213, 2022). "In these cells, abemaciclib decreased CDK6 phosphorylation and downregulated both p-Rb and Rb levels, in accordance with data from literature showing that CDK4/6 inhibitors reduce Rb phosphorylation and concomitantly decrease the expression of total Rb protein in multiple cancer models." (PMID 35936714, 2022). "Selectively targeting senescent cancer cells or SASP-related factors might act as a possible adjuvant therapeutic strategy for NSCLC patients with CDK4/6 inhibitor treatment." (PMID 37181790, 2022). "Better understanding of the limitations of senescence induction by CDK4/6 inhibitors may help in broadening the clinical utility of this class of cancer therapeutics." (PMID 36067171, 2022). "The discovery of CDK4/6 inhibitors is considered a game-changer in cancer treatment." (PMID 35938171, 2022). "Comparisons with standard‐of‐care chemotherapy have given weight to the notion that CDK4/6 inhibitors may be able to replace conventional chemotherapy in this cancer subtype, which represents the majority of metastatic breast cancers." (PMID 35037284, 2022). "This will extend the utility of CDK4/6 inhibitor to the treatment of other cancer types." (PMID 35686110, 2022). "The inhibition of CDK4/6 by palbociclib inhibits the phosphorylation of the retinoblastoma protein (RB), thereby blocking the progression of the cell cycle from the G1 to S phase, which inhibits cancer cell proliferation." (PMID 35350768, 2022). "Considering that CDK4/6 inhibitors have a significant influence on the immune response to various cancer types, it would be intriguing to see if using CDK4/6 inhibitors could increase the efficacy of immune checkpoint inhibitors." (PMID 35530846, 2022). "These facts indicate that the combined treatment of a CDK6 degrader together with inhibitors of CDK2 and CDK4 may hold promising results and should be considered for future investigations, specifically for INK4low cancer cells." (PMID 35326705, 2022). "Taken together, these findings of dual inhibition of AKT-mTOR or CDK4/6 and PD-L1 may constitute an important way of targeting cancer." (PMID 35682571, 2022). "Accordingly, there are nine trials covering many cancer types that combine immune checkpoint agents with CDK4/6 inhibitors; results from these trials may have immense implications on the future of combination therapy." (PMID 35911672, 2022). "A recent in vitro study also demonstrated that activating the MET/FAK signalling axis leads to CDK4/6-independent CDK2 activation and could thus become a target to improve the response of cancers to CDK4/6-targeted therapies." (PMID 35800379, 2022). "Furthermore, ongoing study will yield additional understanding of the potential mechanism(s) of CDK4/6 inhibition in damaging cancer cells, in addition to the cytostatic effects." (PMID 36185294, 2022).
cancer (continued). "Therefore, because of the significant role of CDK4/6 activity in cancer cells, CDK4/6 inhibitors have emerged as well validated targeted therapy for cancer treatment." (PMID 35892870, 2022). "CDK4/6 inhibitors disrupt the signals that stimulate the proliferation of malignant (cancer) cells." (PMID 35337149, 2022). "In addition to the recommendation for genetic counseling, three variants likely associated with an autosomal dominant cancer disposition supported a treatment recommendation, twice for PARP inhibition (BRCA1, CHEK2) and once for CDK4/6 inhibition (CDKN2A)." (PMID 35918329, 2022). "The molecular basis for EMT-mediated drug resistance could be the activation of the PI3K pathway in mesenchymal-like KRASG12C-mutant cancer cells, or, alternatively, a cell cycle alteration leading to CDK4-dependent growth." (PMID 35053550, 2022). "Other cancers overexpress cyclin D1/2/3, CDK4/6, or have lower levels of CDK4/6 inhibitors." (PMID 35911672, 2022). "Senescence and SASP also can be induced by CDK4/6 inhibitors in various cancers." (PMID 37181790, 2022). "We also do not know whether CDK4/6 inhibition-induced acquired vulnerability to oxaliplatin also occurs in other types of cancer cells, or in cells with inherited resistance to CDK4/6 inhibition." (PMID 35664774, 2022). "As such, CDK4/6 are attractive targets for cancer therapy and several CDK4/6 inhibitors including palbociclib, ribociclib and abemaciclib have been approved for treating patients with advanced or metastatic breast cancer, which demonstrate good clinical results." (PMID 35479314, 2022). "The success of these trials, as well as understanding the mechanisms that drive resistance to these inhibitors, should provide an answer as to whether selective inhibitors of CDK4/6 can provide therapeutic benefit in a broader array of cancers." (PMID 36051751, 2022). "Therefore, it is also valuable for studies on cancer therapies to investigate the regulation of CDK4/6 expression." (PMID 35681048, 2022). "Nevertheless, CDK4 appears to be required to keep lysosomal function intact in cancer cells." (PMID 35216401, 2022). "Cancer cells often present a hyperactivated CDK4/6 to sustain their proliferation." (PMID 36065138, 2022). "CDK4/6i are now commonly used as approved and investigative treatments across many cancer types." (PMID 35686110, 2022). "Moreover, CDK4/6 inhibitors given as monotherapy matched to cognate alterations in a variety of cancers have mostly fared poorly." (PMID 33427211, 2021). "Its effect on the cell cycle makes CDK4/6 good candidate targets in almost any cancer type." (PMID 34138895, 2021). "Thus, stimulation of early cell cycle progression through hyperactivation of Cyclin D/Cdk4 clearly presents a crucial growth benefit for cancer cells." (PMID 33806417, 2021). "New data showing effect of the CDK4/6 inhibitors on immune signaling, if validated, may broaden the potential utility of these inhibitors in cancer therapy." (PMID 34327137, 2021). "Interestingly, we observed that CDK4/6 inhibition diminished the impact on viability of many cancer drugs." (PMID 34944934, 2021). "Our findings indicated that knockdown of CDK4 in the two HCC lines inhibited the migration and invasion of cancer cells, implying that CDK4 may play a critical biological function in HCC." (PMID 34784846, 2021). "The loss of p16INK4α leads to excessive activation of CDK4/6 kinase; however, modulation of the p16INK4α/pRB pathway will not inhibit the cancer." (PMID 34660799, 2021). "The cyclin-dependent kinase 4 and 6 (CDK4/6) pathway is commonly activated in many cancers." (PMID 34579759, 2021). "The analysis showed the amplification of CCND1/CDK4/PLK1/CD44 based on percentages of separate genes, with 7% for CCND1, 2.9% for CDK4, 1.7% for PLK1, and 1.8% for CD44 in multiple cancers, including the missense mutation amplifications, deep deletions, and alteration frequencies of these oncogenes." (PMID 34063946, 2021).